SPAG5 (sperm associated antigen 5)
Diseases named in the same sentence as SPAG5 in open-access papers (continued):
Sharing a sentence is not in itself a finding about the gene and the disease.
tumor (27 papers, 2014 to 2025). "In TNBC, increased SPAG5 expression has been associated with tumor progression, chemoresistance, relapse, and poor clinical outcome." (PMID 39164278, 2024). "Recent studies have found that SPAG5 is associated with tumor occurrence, development, invasion, and metastasis." (PMID 31985007, 2020). "High expression of SPAG5 was associated with larger tumor size, poor tumor differentiation, advanced TNM stage, more lymph node metastasis and tumor vascular invasion." (PMID 30089483, 2018). "Immunohistochemical staining with an anti-SPAG5 antibody revealed that tumour grade was significantly and positively (p < 0.05; Methods section) associated with SPAG5 protein levels." (PMID 29093438, 2017). "In addition, RRM2 and PRC1 were associated with some non-tumor diseases such as sclerocystic ovaries and immunoglobulin A glomerulonephritis, whereas SPAG5 was exclusively associated with pregnancy-related diseases." (PMID 39596028, 2024). "SPAG5 is associated with tumorigenesis, apoptosis, and the tumor cell cycle in vitro and in vivo." (PMID 34162370, 2021). "Moreover, Univariate analysis showed that tumor size and high SPAG5 protein expression (p < 0.01) were significantly associated with poor OS." (PMID 30249289, 2018). "Compared with the shNC group, tumor volume and weight were decreased to about 20% following SPAG5 downregulation." (PMID 35138218, 2022). "The nanomaterials were designed to prolong the half-life of siSPAG5 in blood, increase tumor cell-specific uptake, and maximize the efficiency of SPAG5 silencing." (PMID 34162370, 2021). "SPAG5 gene expression was upregulated in tumor tissues with a mean fold change of 4.29 and the mean difference of 2.103." (PMID 32838814, 2020). "The statistical analysis revealed a significant difference between SPAG5 gene expression levels in tumor relative to NATs (p = 0.005)." (PMID 32838814, 2020). "We believe that the study of SPAG5 in tumors requires further in-depth studies, as there are likely many factors that influence SPAG5 in different tumor studies, such as tumor typing, antibody sources, and quality control." (PMID 31985007, 2020). "Correlation studies revealed a significant link between SPAG5 gene expression and tumor size with higher levels in larger tumors." (PMID 32838814, 2020). "High SPAG5 expression was correlated with histological type (P = 0.009); lymph node metastasis (P = 0.001); distant metastasis (P = 0.001); tumor, node, metastasis (TNM) stage (P = 0.001); and prognosis (P = 0.001)." (PMID 31985007, 2020). "Using independent sample t test, the SPAG5 mRNA levels were analyzed in correlation to age, tumor grade, ER, PR, and HER2 status." (PMID 32838814, 2020). "In previous studies, SPAG5 was found increasing in many tumors and considered as a predominant oncogene in tumor promotion and metastasis." (PMID 31690268, 2019). "SPAG5 promotes tumor growth and DNA repair by increasing c-MYC transcriptional activity via interaction with MYCBP." (PMID 30736840, 2019). "SPAG5 promoted tumor growth and decreased cell sensitivity to PARPi via the MYCBP/c-MYC pathway in TNBC." (PMID 30736840, 2019). "In vitro and in vivo data showed that SPAG5 overexpression promoted tumor growth and metastasis, whereas SPAG5 knockdown led to the opposite phenotypes." (PMID 30089483, 2018).
tumor (continued). "In this study, we first found that SPAG5 expression is upregulated in HCC tissues compared with that in non-tumor renal tissues, and its expression level exhibited a negative correlation with patient survival." (PMID 30249289, 2018). "Tumor formation was observed only in 3/6 of mice injected with SPAG5 shRNAs-transfected QGY-7703 cells, but in 5/6 of mice in control group." (PMID 30089483, 2018). "Taken together, these data indicated that knockdown of SPAG5 inhibits HCC tumor growth in vivo and in vitro." (PMID 30249289, 2018). "In SYSUCC cohort, patients with high SPAG5 expression were likely to survive shorter and experience tumor relapse in a shorter time, compared with those with low SPAG5 expression." (PMID 30089483, 2018). "Collectively, these data suggest that SPAG5 contributes to the tumor suppressive activity of miR-363-3p." (PMID 30089483, 2018). "The investigation of the biological function of SPAG5 in HCC demonstrated that SPAG5 exerted oncogenic activities to promote tumor growth and metastasis via interaction with CEP55." (PMID 30089483, 2018). "The results indicated that the subcutaneous tumors of the shSPAG5 group had a smaller volume and lower weight than those of the NC group, demonstrating that the reduction in SPAG5 significantly inhibited tumor growth (p < 0.05)." (PMID 30249289, 2018). "In the present study, our findings showed that SPAG5 expression remarkable increase in HCC tissues compared to the corresponding non-tumor tissues." (PMID 30249289, 2018). "To further investigate SPAG5 influence on HCC tumor growth in vivo, we performed the tumorigenicity assay in nude mice." (PMID 30249289, 2018). "Seven microRNAs were predicted by two bioinformatic algorithms (Targetscan and miRanda) to be the potential upstream regulator of SPAG5, including two tumor suppressors (miR-539-5p and miR-363-3p)." (PMID 30089483, 2018). "High SPAG5 expression was associated with poor tumor differentiation, larger tumor size, advanced TNM stage, tumor vascular invasion and lymph node metastasis." (PMID 30089483, 2018). "Our discovery of SPAG5 as an early gene suggests the presence of increasing chromosomal alterations with decreasing distance to tumour; consistent with our CNA observations." (PMID 29093438, 2017). "Looking at another module that is both significantly and positively correlated with proximity to tumour (module 2), we note the presence of SPAG5, which positively correlates with tumour grade." (PMID 29093438, 2017). "We found that SPAG5 knockdown can contribute to decreased xenograft tumor volume and weight relative to control group." (PMID 27037000, 2016). "We further confirmed that SPAG5 knockdown can significantly inhibit tumor growth and metastasis in vivo." (PMID 27037000, 2016). "Our results indicated that SPAG5 knockdown can drastically inhibit PCa cell proliferation, migration, and invasion in vitro and supress tumor growth and metastasis in vivo." (PMID 27037000, 2016). "By comparing the IHC staining of 193 PLNM-negative and 64 PLNM-positive tumor tissues, we confirmed that SPAG5 was upregulated in PLNM-positive specimens (P=0.0419)." (PMID 24853425, 2014). "The decrease in SPAG5 level will make the chromosomes of cells unable to normally arrange on the equatorial plate during mitosis and make cell division blocked in the G2/M phase, which will restrain the viability of tumor cells and lessen cell activity." (PMID 36237584, 2022). "Tumor volume and weight as well as the lung metastatic tumor number were significantly decreased when SPAG5 was downregulated in A375 cells, further validating our notion that SPAG5 served as an oncogene in MM." (PMID 35138218, 2022). "Subsequently, to determine whether depletion of SPAG5 inhibited tumor cell proliferation, the levels of the proliferation-related protein Ki67 were determined using IHC." (PMID 34162370, 2021). "Recent studies have found that SPAG5 is closely related to tumor occurrence and development." (PMID 31985007, 2020).
tumor (continued). "The results demonstrated a significant link between SPAG5 mRNA levels and tumor size (p = 0.018)." (PMID 32838814, 2020). "Furthermore, we demonstrated that SPAG5 promoted tumor growth by increasing c-MYC transcriptional activity via interaction with MYCBP." (PMID 30736840, 2019). "Functional assays demonstrated that SPAG5 expression promoted tumor growth in vitro and in vivo." (PMID 30736840, 2019). "b SPAG5 mRNA levels in TNBC (n = 165) versus non-tumor tissues(n = 33) from GSE76250 dataset." (PMID 30736840, 2019). "Then, we wanted to further investigate the mechanism by which SPAG5 regulates HCC tumor growth." (PMID 30249289, 2018). "Moreover, function assays revealed that SPAG5 downregulation led to a marked inhibition of proliferation in vitro, and suppression of tumor growth in vivo." (PMID 30249289, 2018). "shRNAs against SPAG5 significantly reduced the tumor metastasis in mice." (PMID 30089483, 2018). "Increased expression of SPAG5 was found in tumor metastasis, compared with the primary tumor." (PMID 30089483, 2018). "Furthermore, a cohort consisting of 93 patients with tumor embolus was recruited to determine the expression of SPAG5 in metastatic tumor tissues." (PMID 30089483, 2018). "In vivo tumor formation assay was used to examine the effect of SPAG5 on tumor growth." (PMID 30089483, 2018). "SPAG5 silence tumor tissues showed reduced staining for SPAG5." (PMID 27037000, 2016). "SPAG5 silence can lead to significantly reduced tumor volume and weight relative to control mice." (PMID 27037000, 2016). "In addition to cell growth and proliferation, cell mobility is also important to tumor severity; therefore, we analyzed the migration and invasion abilities of SPAG5 knockdown HeLa cells." (PMID 24853425, 2014). "In addition, we found that the expressions of FOXM1, ADAM17, NOTCH1 and N-cadherin were decreased in SPAG5-downregulated tumor tissues, while E-cadherin expression was increased, highlighting the role of SPAG5 in downregulation of the expression of FOXM1, ADAM17 and NOTCH1, and inhibiting EMT." (PMID 35138218, 2022). "The results suggested that SPAG5 might be involved in tumor progression." (PMID 34796102, 2021). "Moreover, SPAG5 knockdown resulted in marked anti-tumor effects in a number of human malignancies." (PMID 34162370, 2021). "In addition, knockdown of SPAG5 tumor cells exhibited enhanced apoptosis in vitro and in vivo." (PMID 30249289, 2018). "Furthermore, knockdown of SPAG5 tumor cells exhibited enhanced apoptosis." (PMID 30249289, 2018). "This probably may be due to the fact that overexpression of SPAG5 was associated with infaust clinical factors, including poor tumor histological differentiation, large tumor volume, advanced TNM stage, lymph node metastasis status, and tumor vascular invasion." (PMID 34796102, 2021). "In vivo tumor metastasis models demonstrated that more lung nodules were depicted in mice injected with PLC8024 and Huh7 cells with SPAG5 overexpression." (PMID 30089483, 2018). "We also analyzed gene expression profile of paired metastatic (LTL313H) and non-metastatic (LTL313B) PCa tissue xenograft lines derived from one patient’s primary tumor, LTL313H showed higher expression of SPAG5 relative to LTL313B." (PMID 27037000, 2016). "In our recent study, we confirmed that SPAG5 protein was elevated in PLNM-positive patients and clearly upregulated in tumor tissues compared with paired ANT." (PMID 24853425, 2014). "The interaction of SPAG5 with key hub genes such as MDM2 and CDK1 not only reinforces its role in tumour suppression through negative regulation but also highlights its potential in moderating the phenotypic and genomic alterations associated with AML progression." (PMID 39762615, 2025). "Consistent with the reduced SPAG5 protein levels induced by FeSiNTs-siSPAG5, western blotting showed significantly decreased expression of PI3K/AKT/mTOR signaling pathway members in the tumor mass." (PMID 34162370, 2021).
tumor (continued). "Other important clinicopathological indicators, such as age, tumor size and location, and tumor grade were not correlated with SPAG5 expression." (PMID 31985007, 2020). "SPAG5 mRNA was significantly upregulated in TNBC tumor tissues compared with that in the paired ANTs in our cohort (p = 0.008), which is consistent with the findings in the GSE76250 TNBC dataset (p < 0.001), and SPAG5 protein was also unregulated." (PMID 30736840, 2019). "The analysis of the clinical features of HCC patients revealed that SPAG5 overexpression was closely correlated with Tumor size (p < 0.01), but was not significantly correlated with Age, Gender, Tumor Number, and Tumor location." (PMID 30249289, 2018). "This might be attributed to the fact that high expression of SPAG5 was correlated with unfavorable clinical parameters, including poor tumor differentiation, larger tumor size, advanced TNM stage, tumor vascular invasion and lymph node metastasis." (PMID 30089483, 2018). "The qRT-PCR data revealed that the average fold change of SPAG5 mRNA expression in tumor tissues was significantly higher than that in paired nontumor tissues (p < 0.01)." (PMID 30249289, 2018). "In addition, the present study failed to validate the SPAG5-mediated TNBC progression and chemoresistance in vivo xenograft tumour models, which mimic the human tumour microenvironment to guide the clinical application of SPAG5." (PMID 38610947, 2024). "The relative expression levels of CDKN3, MKI67, CEP55, SPAG5, AURKA, TOP2A were consistent with the results of bioinformatics analysis (P < 0.05), while the expression levels of UBE2C, CHEK1 and BIRC5 in tumor samples were not significantly different from adjacent normal samples." (PMID 35178291, 2022).
SPAG5 also shares sentences with these, for which no sentence is quoted: colon cancer (2 papers); diabetic nephropathy (1); gallbladder carcinoma (1); lung diseases (1); metastasis (1); pancreatic cancer (1); prostate tumours (1); stomach cancer (1); viral infections (1).